IRF8 (interferon regulatory factor 8)
Diseases named in the same sentence as IRF8 in open-access papers (continued):
Sharing a sentence is not in itself a finding about the gene and the disease.
tumor (continued). "Of note, several studies have shown that IRF8 is involved in inhibiting multiple non-hematopoietic cancer cell growth and progression, indicating its potential tumor-suppressive activities and its expression is regulated by DNA methylation." (PMID 38472940, 2024). "We show here that COX2 expression at the tumor margin limits CD8+ T-cell infiltration into the tumor core, which involves at least in part reduced cytokine and chemokine expression (IRF8, CLEC9a, CXCL9, CXCL10, CXCL11, and IL27) that promotes directional immune cell migration." (PMID 39356141, 2024). "The percentage of IRF8+ M-MDSC and TAMs and the expression of CD80 and CD86 in TAMs was increased in Pdcd1f/fLysMCre tumor-bearing mice compared to Pdcd1f/f tumor-bearing mice." (PMID 36581713, 2023). "The inhibition of ferroptosis significantly decreased CTL-induced control tumor cell death, but not mutant IRF8-expressing CMS4.K79E tumor cell death." (PMID 36672246, 2023). "For example, the tumor-associated macrophages (TAMs) could be engineered to directly attack tumor cells by inhibiting SHP substrate 1, or spare the T Cell from exhaustion by losing TAM antigen presentation in an IRF8-dependent manner." (PMID 37180717, 2023). "In human cancer patients, nivolumab responders have a significantly higher IRF8 expression level in their tumor cells as compared to the non-responders." (PMID 36672246, 2023). "Remarkably, expression levels of key AST factors, IKZF1, NFE2, and IRF8, were significantly enriched in CTCs that were, however, largely absent in primary tumor cells." (PMID 36991428, 2023). "To determine whether tumor cell-expressed IRF8 regulates CTL-induced ferroptosis, we used the tumor cell line CMS4 and the CMS4 tumor cell-specific 2/20 CTL line." (PMID 36672246, 2023). "The results showed a significant negative correlation between tumor purity and IRF8, CD53, ITGB2, HLA‐DPB1, and IL7R expression." (PMID 35845349, 2022). "Indeed, IL-33 expression correlated strongly with CD8A and granzyme B as well as genes like BATF3, IRF8, THBD, CLEC9, and XCR1 that are required for tumor antigen cross-presentation functionality of CD103+ dendritic cells (DCs)." (PMID 36256464, 2022). "Therefore, in addition to functioning as a repressor of SPP1 in immune cells such as MDSCs and ILCs, IRF8 not only functions as an intrinsic tumor suppressor but also suppresses tumorigenesis and progression through repressing OPN expression in tumor cells." (PMID 36078039, 2022). "To test this idea, we used MDSCs (CD11b+Gr-1+ cells) isolated from the spleens of Irf8–/– mice, a model that generates high numbers of suppressive splenic MDSCs, even in the absence of tumor implantation." (PMID 36453551, 2022). "Recently, a scRNA-seq study of six metastatic omental tumors that derived from primary HGSOCs unraveled the genetic signatures of immune cell subsets within the tumor microenvironment and identified NR1H2+ IRF8+ and CD274+ macrophage clusters, which were suggested with an anti-tumor response." (PMID 35935940, 2022). "In summary, our study found that low expression of IRF8 and its four key coexpressed genes in HCC tissues were negatively correlated with tumor purity, and positively correlated with immune cell infiltration, and could be used to predict patient survival." (PMID 35845349, 2022). "Therefore, we suggested that the level of IRF3, IRF6, IRF7, IRF8 and IRF9 were upregulated in tumor tissues of PC." (PMID 35012444, 2022). "Since transfer of IRF8-deficient MDSCs could retain the dominant suppressive features of these aggressive tumor models, even in the presence of BRQ, the impact of BRQ on IRF8 modulation deserves further study." (PMID 36453548, 2022). "The results showed that the tumor sizes for PANC1 and BxPC3 in irf8−/− were slightly increased." (PMID 35742884, 2022). "Besides IL-6, IRF-8 was described as a key negative regulator of MDSC, as IRF8-/- mice display marked accumulation of MDSC in a tumor model." (PMID 33692788, 2021).
tumor (continued). "It was observed that tumour cells were more invasive when cultured in vitro alongside IRF-8 KO splenocytes rather than WT splenocytes." (PMID 34085677, 2021). "Genes upregulated in both tumor and TAS of BA PCa patients as compared to WA included cell cycle markers CD19, CD2, CD53 and CD80, interferon response factor 8 (IRF8), phosphoinositide 3-kinase (PIK3CA), mechanistic target of rapamycin (mTOR), and metastasis-associated protein S100A4." (PMID 34316327, 2021). "Moreover, analysis of immune contexture of tumor tissues indicates a strong correlation between activated and effector CD8+ T cell infiltration and tumoral IRF8 expression." (PMID 33766090, 2021). "These authors also showed that the blockage of STAT-mediated IRF-8 downregulation could prevent MDSC accumulation and dysregulation of the immune response in tumor." (PMID 33692788, 2021). "Transcriptomics and proteomics analyses revealed complex effects on the tumor microenvironment triggered by hetIL-15 therapy, including increased levels of IFN-γ and XCL1 with intratumoral accumulation of XCR1+IRF8+CD103+ conventional type 1 dendritic cells (cDC1)." (PMID 32461349, 2020). "Certain transcription factors, such as CCAAT/enhancer binding protein-α (C/EBPα), and interferon regulatory factor-8 (IRF-8), are instrumental for normal myeloid cell development, differentiation and function and they can be targets of tumor-derived factors (TDFs)." (PMID 32849585, 2020). "CD103+CD11b- DCs require the basic leucine zipper transcription factor ATF-like 3 (BATF3) and interferon regulatory factor 8 (IRF8) for their development and are equipped to cross-present viral, tumor, and self-antigens; the functional human equivalent of CD103+CD11b- DCs is the CD141hi DC subset." (PMID 31188899, 2019). "FLT3L treatment in vivo promoted the differentiation of CD103+ DC progenitors in the bone marrow and their expansion at the tumor site by enforcing IRF8 signaling, resulting in accumulation of immature CD103+ DCs and accumulation of Treg cells at the tumor site." (PMID 30683885, 2019). "Together, these results suggest tumors can shift the net balance of immune-stimulatory and immune-suppressive BM and peripheral myeloid cells via alteration of IRF8 expression through regulation of inflammatory cytokines like GCSF, thereby blunting anti-tumor immunity." (PMID 29593283, 2018). "IRF8 has been shown to positively regulate the apoptosis of myeloid cells and nonhematopoietic tumor cells." (PMID 29357389, 2018). "We found GMPs, MDPs, and CDPs from tumor-bearing mice failed to upregulate proteins indicative of the cDC program (e.g., Irf8, Zbtb46, Cd209a, Spib, Batf3, and Bcl11a)." (PMID 29593283, 2018). "Also, we neutralized Ly6G in IRF8−/− mice and measured PyMT-mCh-OVA tumor growth and found tumors grew at similar rates." (PMID 29593283, 2018). "The prediction was that if the enhanced rate of tumor growth observed with CMS4-IRF8lo cells was due at least in part to higher MMP3 levels, then attenuating MMP3 expression altogether should reduce this IRF8-dependent growth advantage." (PMID 26008967, 2015). "The IRF8 methylation level was significantly higher in the tumor tissues than in matched non-malignant lung tissues (P<0.0001)." (PMID 25120651, 2014). "IRF8 was more frequently methylated in tumor tissues compared with matched non-malignant lung tissues, as defined by a predetermined cut-off value (P<0.0001)." (PMID 25120651, 2014). "Our earlier work led to the identification of interferon regulatory factor-8 (IRF-8) as a positive regulator of response to Fas-mediated killing of non-hematopoietic tumor cells." (PMID 23028998, 2012). "In addition, the authors investigated the long-term fate of the mutant mice to show cooperative tumor suppressive functions for IRF4 and IRF8 in both myeloid and lymphoid cells." (PMID 22003407, 2011).
tumor (continued). "To investigate whether inhibition of ERK activation prevents TRIM63 phosphorylation and IRF-8 degradation, we found that treatment of BRAF-mutant tumor cells with Dabrafenib and Vemurafenib suppressed TRIM63 phosphorylation at S69 while concurrently increasing IRF-8 protein levels." (PMID 41315179, 2025). "Therefore, IRF8-encoding plasmid DNA lipid nanoparticle therapy is a potentially effective approach to increase IRF8 expression in the target tumor cells to convert ICI immunotherapy non-responders to responders, which warrants further study." (PMID 36672246, 2023). "Both the WT and IRF8.KO tumor cells were not sensitive to erastin." (PMID 36672246, 2023). "However, unlike IRF1, IRF8 deletion did not change the expression of SLC3A2 or SLC7A11 in tumor cells." (PMID 36672246, 2023). "IRF8 therefore also functions as a tumor suppressor in non-hematopoietic cells." (PMID 36078039, 2022). "However, in an already established tumor, the maturation of myeloid cells to macrophages is blocked by multiple factors and mechanisms, such as tumor-derived growth factors (STAT3, IRF8, C/EBPβ, Notch, adenosine receptors A2B signaling, NLRP3), hypoxia, and negative feedback loops." (PMID 34557407, 2021). "Conversely, 90% of LC/A HN MB (n = 19 of 21) showed many clusters of pS6-IR cells, which were negative for IRF8 expression, indicating that mTORC1 was hyperactivated in tumor cells only in LC/A MB and might play a role in the acquisition of LC/A features." (PMID 34673573, 2021). "Further, CD103+ DCs are a distinct DC population that is uniquely dependent on IRF8 and Batf3 transcription factors and predominantly expresses CCR7 in human tumors, expression of which was used as a molecular proxy for CD103+ DCs in clinical tumor gene expression data sets." (PMID 32759497, 2020). "Interestingly, unlike Notch1, Ikaros and IRF8 expressions were found to be significantly elevated in the “stunted” DN2-T cells isolated from the thymi of tumor-bearing mice." (PMID 32582141, 2020). "Furthermore, IRF8 expression was, again, downregulated in progenitors from PyMT-B6 tumor-bearing mice but was not downregulated in progenitors from PyMT-B6 GCSFKO mice." (PMID 29593283, 2018). "Based on our results showing IRF8 overexpression in the DLBCL tumor microenvironment and previous findings showing that IRF8 inhibits Th17 differentiation in CD4+T cells in mice, we investigated whether IRF8 affected the generation of Th17 cells in the tumor microenvironment in vitro." (PMID 28537908, 2017). "Comparisons of tumor tissues with matched non-malignant lung tissues indicated that aberrant methylation of IRF8 gene was a tumor-specific event (Fisher’s exact probability test; P<0.0001), despite the fact that tumor tissues consisted of mixtures of tumor cells and non-malignant cells." (PMID 25120651, 2014). "The tumor suppressor activity of IRF8 has been observed in non-hematopoietic tumors." (PMID 25120651, 2014). "Moreover, similar results with TSA were observed in a second tumor cell model, suggesting that the effects of HDACi on IRF-8 expression were not tumor model-specific." (PMID 23028998, 2012). "We have hypothesised that DNMTi can also act through the activation of the IFNγ-signalling pathway components and we therefore focused on the expression levels of the selected genes from this pathway, namely interferon responsible factors 1 (IRF-1) and 8 (IRF-8) and STAT-1 in tumour cells." (PMID 22015556, 2011). "Indeed, interventions that target atypical myelopoiesis by enhancing IRF-8 expression demonstrated to abrogate MDSC-mediated immunosuppression and to promote MDSCs differentiation in effector myeloid cells including DCs and mature neutrophils with anti-tumor activity." (PMID 32849585, 2020). "However, the impact of IRF8 expression on tumor growth could not be explained solely by its effects on regulating apoptotic response." (PMID 26008967, 2015).
tumor (continued). "The differences noted in respect to tumor burden and the TME infiltrate were not related to the levels of ectopic expression of IRF8 WT or mutants, which were tightly controlled." (PMID 38996030, 2024). "ER−breast cancers (BCs) and triple -negative breast cancers (TNBCs) also offer little to no IRF8 expression, indicating that impaired cGAS/STING signaling supports tumor growth and metastasis due to decreased antitumor CD8+T cell infiltration." (PMID 37380989, 2023). "Tumor-infiltrating B cells represented between 0.05% and 0.6% of CD45+MHCII+ and did not stain positive for CD11c, XCR1 and IRF8." (PMID 32461349, 2020). "We analyzed the expression of IRF8 by IHC in paraffin-embedded tumor specimens from 67 DLBCL patients, of which five showed no IRF8 expression and the others showed various levels of IRF8 expression." (PMID 28537908, 2017). "However, within the tumor microenvironment (TME), tumor cells and their targets such as STAT3, IRF8, C/EBPβ, and Notch can inhibit the differentiation of IMCs." (PMID 37857728, 2023). "We observed a significant negative correlation between CD11c+ LAMP3+ IRF8+ DCs and TLS density, reinforcing the notion that LAMP3+ DCs contribute to TLS suppression and exert immunosuppressive effects within the tumor microenvironment, with IRF8 playing a key regulatory role in this process." (PMID 41190765, 2026).
infection (68 papers, 2009 to 2026). The state of being infected such as from the introduction of a foreign agent such as serum, vaccine, antigenic substance or organism. "The major finding of our study was the association of the reduction of IRF8 expression in pDC with a rising rate of infections requiring hospitalization occurring in the following year." (PMID 37508555, 2023). "Vice versa, deficiency of IRF8 has been attributed to an elevated risk for infections in human and mice studies." (PMID 37508555, 2023). "The deficiency of transcription factor IRF8 is known to be associated with increased susceptibility to infections and reduced antiviral and antimicrobial defense mechanisms." (PMID 37508555, 2023). "The current study analyzed the expression patterns of IRF8 and assessed its association with the risk of infections in 79 dialysis patients compared to 44 healthy controls." (PMID 37508555, 2023). "IRF8 is a key regulator of apoptosis inhibitory protein, which can defend against pathogenic infection." (PMID 37593742, 2023). "Our results suggest that reduced IRF8 expression in pDCs is a potential risk factor predisposing dialysis patients to serious infections." (PMID 37508555, 2023). "In a multivariable Cox regression analysis, reduced IRF8 expression in pDC exerted a minor effect on the risk of developing subsequent infections requiring hospitalization in a one-year follow-up." (PMID 37508555, 2023). "A 915C> T mutation (R294C) resembles IRF8 KO mice in accumulating immature myeloid cells (IMCs) and causes susceptibility to infection in mice." (PMID 36078039, 2022). "Loss of IRF8 expression or function often leads to impaired immune response to infection and hematopoietic malignancies." (PMID 36078039, 2022). "This is consistent with previous reports where increased susceptibility to infections was reported in Irf8−/− mice." (PMID 34379515, 2021). "Additive effects of the deficiency and dysfunction of immune cells in IRF8 deletion mice result in susceptibility to infection." (PMID 34365741, 2021). "The macrophage IRF8/IRF1 regulome was found required for protection against infection and is associated with chronic inflammation." (PMID 34290700, 2021). "IRF8 plays a critical role in immune cell functions, protection against infections, and susceptibility to inflammatory diseases." (PMID 34067819, 2021). "Partial or total loss-of-function of IRF-8 results in decreased resistance to infections with intracellular pathogens such as Toxoplasma gondii in mice and Mycobacterium tuberculosis in humans." (PMID 28968468, 2017). "During primary infection, high worm burdens in IRF-8-deficient mice were associated with marked expansion of MDSC in mesenteric lymph node (MLN) and spleen." (PMID 28968468, 2017). "Irf8-deficient macrophages are also extremely susceptible to ex vivo infection by intracellular pathogens." (PMID 23853600, 2013). "The list of IRF8-bound genes by ChIP-seq was intersected with the list of genes regulated by PbA in a strain, infection and Irf8-associated fashion from the two-factor ANOVA analysis." (PMID 23853600, 2013). "BXH2 mice harbor a severely hypomorphic allele at Irf8 (Irf8R294C) that causes susceptibility to infection with intracellular pathogens including Mycobacterium tuberculosis." (PMID 23853600, 2013). "IRF8 is a member of the interferon regulatory factors that has a pivotal role in mediating resistance to pathogenic infections and in promoting the differentiation of myeloid cells." (PMID 22879909, 2012). "Macrophages from IRF8-deficient mice remain immature, including altered expression of intrinsic macrophage anti-microbial defenses, and are susceptible to ex vivo infection with M. bovis, Salmonella typhimurium, and Legionella pneumophila." (PMID 21731497, 2011). "Macrophage maturation including expression of cytocidal function is also impaired in IRF8-deficient mice, and their macrophages are susceptible to infection with intracellular pathogens in vitro." (PMID 21731497, 2011).